ZDHHC9 (zDHHC palmitoyltransferase 9)
Diseases named in the same sentence as ZDHHC9 in open-access papers (continued):
Sharing a sentence is not in itself a finding about the gene and the disease.
cognitive deficits (5 papers, 2015 to 2025). "In summary, this study characterises neurophysiological processing in the ZDHHC9‐associated neurodevelopmental condition and provides a proof‐of‐concept for using neural network models to investigate the mechanistic origins of cognitive disorders." (PMID 40308169, 2025). "Mutations in ZDHHC9 are associated with susceptibility to focal seizures and specific cognitive impairments intersecting with the RE spectrum." (PMID 26000327, 2015). "There are several possible explanations for the higher degree of comorbidity between seizure susceptibility and cognitive impairments amongst males with ZDHHC9 mutations as compared to idiopathic RE." (PMID 26000327, 2015). "An important caveat is that cognitive deficits in males with ZDHHC9 mutations were more uniform than previously observed in RE and occur on a background of mild to moderate ID." (PMID 26000327, 2015). "MRI studies of individuals with ZDHHC9‐associated ID identified neuroanatomical differences that may increase the risk for epilepsy and cognitive impairments, such as reductions in cortical thickness and connectomic deviations." (PMID 40308169, 2025). "Specific cognitive deficits differentiated males with ZDHHC9 mutations from XLID comparison subjects and converged with reported linguistic and nonlinguistic deficits in idiopathic RE: impaired oromotor control, reduced verbal fluency, and impaired inhibitory control on visual attention tasks." (PMID 26000327, 2015).
colon cancer (4 papers, 2007 to 2026). "zDHHC9 knockdown promoted colon cancer cell proliferation in vitro but decreased tumor growth in vivo, increasing immune cell infiltration and enhancing T cell‐mediated cytotoxicity." (PMID 39429488, 2024). "In human DLD‐1 and mouse MC38 colon cancer cell lines, zDHHC9 expression promoted IFN‐γ‐induced JAK/STAT1 activation and PD‐L1 upregulation." (PMID 39429488, 2024). "zDHHC9 expression is upregulated in colon cancer and correlates with bad prognosis." (PMID 39429488, 2024).
Rolandic epilepsy (4 papers, 2015 to 2025). "Most notably, Zdhhc9 KO mice have seizures, reminiscent of the rolandic epilepsy reported in many human patients with ZDHHC9 mutation." (PMID 41031565, 2025). "Seizure histories and EEG features amongst ZDHHC9 mutation cases shared characteristics with rolandic epilepsy (RE)." (PMID 26000327, 2015). "Loss‐of‐function ZDHHC9 variants are associated with X‐linked intellectual disability (XLID), rolandic epilepsy (RE) and developmental language difficulties." (PMID 40308169, 2025).
leukemia (3 papers, 2023 to 2025). A malignant (clonal) hematologic disorder, involving hematopoietic stem cells and characterized by the presence of primitive or atypical myeloid or lymphoid cells in the bone marrow and the blood. "Conversely, ZDHHC9 expression was markedly lowest in cell lines derived from leukemia and lymphoma tissues in both datasets." (PMID 36760531, 2023).
lung adenocarcinoma (3 papers, 2017 to 2025). A carcinoma that arises from the lung and is characterized by the presence of malignant glandular epithelial cells. "According to our data, increased ZDHHC9 is observed in lung adenocarcinoma, but its high expression is correlated with better rates of survival." (PMID 29285217, 2017). "Survival curve analysis revealed that lung adenocarcinoma patients with high expression of ZDHHC9, BTNL9, GNG11 or CPED1 are correlated with better survival outcomes." (PMID 29285217, 2017). "The mRNA expression of BTNL9, GNG11, or CPED1 is downregulated in lung adenocarcinoma when compared to normal tissue, and ZDHHC9 is upregulated." (PMID 29285217, 2017).
schizophrenia (3 papers, 2017 to 2025). A major psychotic disorder characterized by abnormalities in the perception or expression of reality. "Given the conditions, dysregulated palmitoylation modifications on specific zDHHC enzymes likes zDHHC9, zDHHC13, and zDHHC21 are targeted in AD, HD, schizophrenia, and glioma, suggesting as a therapeutic approach." (PMID 40831763, 2025).
Anxiety (2 papers, 2018 to 2025). Intense feelings of nervousness, tension, or panic often arise in response to interpersonal stresses. "The EPM is a classical test for anxiety and the Zdhhc9 mutant mice spent significantly longer than WT animals in the more aversive open arms of the EPM, associated with lower levels of anxiety." (PMID 29944857, 2018). "The thygmotactic behaviour of the Zdhhc9 mutant mice during the habituation phase of the OFT is consistent with reduced anxiety levels." (PMID 29944857, 2018). "In addition, performance in both the open field and in an elevated plus maze (EPM, in which the KO mice spend significantly more time in the open arms) suggests that Zdhhc9 KO mice also have decreased levels of anxiety." (PMID 41031565, 2025). "As the amygdala is important in processing emotional reactions such as anxiety and fear, this brain region could possibly be affected by the disruption of Zdhhc9 and this merits analysis in future studies." (PMID 29944857, 2018).
colon adenocarcinoma (2 papers, 2007 to 2022). "Microarray analysis on pooled samples has previously identified ZDHHC9 (DHHC9) to be upregulated in colon adenocarcinoma compared to normal colon mucosa." (PMID 17519897, 2007).
colorectal tumors (2 papers, 2007 to 2019). "In addition, upregulation of ZDHHC9 has been found in colorectal tumors." (PMID 30658672, 2019).
developmental delay (2 papers, 2023 to 2024). "Note that some features of this proband do overlap with those of the autosomal dominant disorder caused by pathogenic variants in the ZDHHC9 gene, such as developmental delay, downslanting palpebral fissures, and behavior issues." (PMID 38565639, 2024).
glioma (2 papers, 2023 to 2025). A benign or malignant brain and spinal cord tumor that arises from glial cells (astrocytes, oligodendrocytes, ependymal cells). "Knockdown of zDHHC9 in an athymic nude mouse model bearing glioma enhances the survival time of mice." (PMID 38293675, 2023). "Upregulation of both the mRNA and protein expression of zDHHC9 in gliomas correlates with tumor grade." (PMID 38293675, 2023). "Glioma patients with high expression of zDHHC9 have shorter survival prognosis." (PMID 38293675, 2023).
myeloid malignancies (2 papers, 2023). "In this study, we uncovered a previously unappreciated role for RAB27B in regulating NRAS palmitoylation, subcellular trafficking, and signaling in myeloid malignancies, in part via interacting with the palmitoyl acyltransferase ZDHHC9." (PMID 37317963, 2023). "Ren and colleagues have discovered a role of the CBL/JAK2/RAB27B/ZDHHC9 signaling axis in regulating NRAS trafficking to the plasma membrane for activation by palmitoylation in myeloid malignancies." (PMID 37317974, 2023).
renal fibrosis (2 papers, 2023 to 2025). A final common manifestation of a wide variety of chronic kidney diseases characterized by glomerulosclerosis and tubulointerstitial fibrosis. "However, ZDHHC9 expression is significantly downregulated during renal fibrosis." (PMID 39913299, 2025). "We hypothesized that Zdhhc9 knockout promotes renal fibrosis by upregulating β-catenin expression." (PMID 37865665, 2023). "We found that ZDHHC6, ZDHHC9, and ZDHHC18 could catalyze HRAS palmitoylation but that the expression of ZDHHC6 and ZDHHC9 was downregulated during renal fibrosis." (PMID 39913299, 2025).
epilepsy syndrome (1 paper, 2015). A syndrome that has a characteristic cluster of clinical features and/or lectroencephalographic (EEG) findings that reflect underlying epileptic activity. "This issue can only be addressed via empirical investigation to establish the rates of ZDHHC9 mutations amongst individuals ascertained for different epilepsy syndromes." (PMID 26000327, 2015).
Epileptic encephalopathy (1 paper, 2020). A condition in which epileptiform abnormalities are believed to contribute to the progressive disturbance in cerebral function. "ZDHHC9, ITPR1, and GLRA1 showed meaningful variants in the gene panel for neurodevelopment disorders during reanalysis but were not actually included in the gene panel for epileptic encephalopathy." (PMID 32695065, 2020).
erectile dysfunction (1 paper, 2026). Persistent or recurrent inability to achieve or to maintain an erection during sexual activity. "To explore the therapeutic potential of targeting this pathway, we developed siRNA against Zdhhc9 encapsulated in lipid nanoparticles (siZdhhc9-LNPs), which effectively suppressed Zdhhc9 expression in the corpus cavernosum and ameliorated erectile dysfunction in DMED mice." (PMID 42085610, 2026).
expressive language deficits (1 paper, 2017). "Loss of function mutations in ZDHHC9 result in pervasive differences in white matter volumes and integrity, alongside a cognitive profile that includes profound expressive language deficits." (PMID 28168288, 2017).
focal epilepsy (1 paper, 2015). A seizure caused by a localized disorder. "Having detected the unexpectedly high frequency of focal epilepsy amongst males with ZDHHC9 mutations, we posed the hypothesis that specific cognitive deficits showing similarity to idiopathic RE might differentiate ZDHHC9 from other causes of XLID." (PMID 26000327, 2015).
influenza (1 paper, 2025). An acute viral infection of the respiratory tract, occurring in isolated cases, in epidemics, or in pandemics; it is caused by serologically different strains of viruses (influenzaviruses) designated A, B, and C, has a 3-day incubation period, and usually lasts for 3 to 10 days. "We found that resting DCs express high levels of Zdhhc9, which is consistently downregulated upon CpGB stimulation in GM‐DCs and following influenza exposure in human pDCs." (PMID 40828036, 2025). "In particular, the expression of Zdhhc9 was repressed during TLR9 sensing in GM‐DCs, but also when human pDCs were exposed to influenza." (PMID 40828036, 2025).
Pleural effusion (1 paper, 2021). The presence of an excessive amount of fluid in the pleural cavity. "ZDHHC9 has been shown to be associated with myeloid cells in pleural effusion." (PMID 34575089, 2021).
cancer (21 papers, 2007 to 2026). A tumor composed of atypical neoplastic, often pleomorphic cells that invade other tissues. "Together, these findings support an immunosuppressive role for ZDHHC9, which is associated with an unfavorable prognosis in cancer." (PMID 40828036, 2025). "Taken together, these data establish ZDHHC9 as a driver of an immune-tolerant milieu in multiple cancers, including BC, which likely contributes to its association with unfavorable clinical outcomes." (PMID 40740766, 2025). "Although palmitoyl transferases, particularly ZDHHC9, have been associated with the progression of various cancers, their specific role in BC remains incompletely understood." (PMID 40740766, 2025). "Subsequently, immunohistochemical (IHC) analysis and western blotting verified that ZDHHC9 expression was elevated in TNBC cancer tissues and that elevated expression of ZDHHC9 was associated with the poor survival of patients with TNBC." (PMID 37875591, 2023). "Here, we demonstrate that the palmitoylation enzyme Zinc Finger DHHC-Type Containing 9 (ZDHHC9) activates the mTOR signaling pathway, thereby accelerating cancer progression and highlighting its potential role in RCC." (PMID 41856969, 2026). "First, the correlation between ZDHHC9 expression and genomic features, along with immune-related indicators—including mutations, neoantigens, CTA (cancer testis antigens), and TCR/BCR diversity—was assessed." (PMID 40740766, 2025). "Initially, ZDHHC9 mRNA expression levels were examined across 33 cancers through the TCGA and GTEx databases." (PMID 40740766, 2025). "In this study, drugs that exerted effects in contrast to those of Zdhhc9 knockout on cell survival were screened across the Cancer Dependency Map." (PMID 37865665, 2023). "ZDHHC9 palmitoylates PD-L1 to maintain its protein stability and cell surface distribution, protecting cancer cells from the immune surveillance of T cells." (PMID 34829931, 2021). "The interaction between ZDHHC9 and PD-L1 is affirmed, knockdown of ZDHHC9 in cancer cells induces a significant reduction of PD-L1 palmitoylation and sensitizes T-cell-mediated killing, hence inhibiting tumor growth." (PMID 31258527, 2019). "The function of ZDHHC9 in cancers is unclear, although inactivation of ZDHHC9 can reduce leukemogenic effects through repression of oncogenic NRAS." (PMID 29285217, 2017). "One of these was EST AA232508, identified as part of the ZDHHC9 gene and strongly upregulated in all cancer stages." (PMID 17519897, 2007). "Since multiple factors, including clinical variables like age, tumor stage, and cancer subtype, influence BC prognosis, univariate and multivariate Cox regression analyses were executed by integrating ZDHHC9 expression alongside these pathological characteristics." (PMID 40740766, 2025). "This may be particularly relevant in cancer, where aberrant ZDHHC9 expression has been reported across multiple tumor types and proposed as a potential prognostic marker." (PMID 40828036, 2025). "In addition, IHC analysis revealed that ZDHHC9 expression was significantly higher in cancer tissues than in adjacent normal tissues." (PMID 37875591, 2023). "Screening for drugs that suppress the effects of Zdhhc9 knockout on cell survival across the Cancer Dependency Map and considering the generality between cell lines and the reproducibility of effects, iproniazid was selected as a drug to induce DHHC9 expression." (PMID 37865665, 2023). "The expression of ZDHHC9 was examined at the pan-cancer level." (PMID 37875591, 2023). "Furthermore, ZDHHC9 has also been reported to be overexpressed in diverse types of cancers." (PMID 38177255, 2024). "To predict the cancer-promoting characteristics and prognosis of TNBC using the combination of the four genes, we calculated risk coefficients for co-expression integration and constructed a risk model with the following formula: risk score = 2*TBC1D24 + 1*TRIM67 + 1*QRSL1 + 1.8*ZDHHC9." (PMID 37875591, 2023).
cancer (continued). "Pan-cancer analysis across 33 human cancer types reveals ZDHHC9 mRNA upregulation in 20 cancers, and TISIDB data indicates that ZDHHC9 negatively correlates with key immune regulators, further supporting its role in tumor progression." (PMID 40335986, 2025). "Thus, there is a positive feedback loop for ZDHHC9, ERK1/2, and APLNR in the NCP model that exacerbates pain-induced inflammatory responses and drug resistance in cancer." (PMID 38164190, 2024). "Although it is unclear how ZDHHC9 in the tumor cells affects PD-L1 expression level on the surrounding immune cells, this study reported the non-autonomous function of ZDHHC9 in regulating the cancer immune response for the first time." (PMID 37759431, 2023). "Accordingly, inhibition of PD-L1 palmitoylation with a competitive inhibitor 2-BP and knock-out palmitoyltransferase ZDHHC9/DHHC3 decreases the cell surface membrane PD-L1 level and exhausts the storage of PD-L1 in endosomes, thereby enhancing immune clearance of cancer cells." (PMID 34829931, 2021). "Notably, two specific genes, ZDHHC9 (a palmitoyl-acyltransferase) and ABHD17C (a de-palmitoyl-acyltransferase), displayed significant dysregulation across more than 10 human cancer types and exhibited correlation with cancer subtypes in seven human cancer types." (PMID 37978524, 2023).
tumor (21 papers, 2007 to 2026). "A novel insight from our single-cell RNA sequencing analysis is that ZDHHC9-overexpressing BC cells may shape the TME by engaging tumor-associated macrophages (TAMs) through the macrophage migration inhibitory factor (MIF) pathway." (PMID 40740766, 2025). "The results suggested that ZDHHC9 expression was negatively associated to immune, stromal, and total ESTIMATE scores (P < 0.001), suggesting that higher ZDHHC9 expression is linked to reduced immune and stromal infiltration, resulting in increased tumor purity." (PMID 40740766, 2025). "Knockdown of ZDHHC9 in the murine TNBC cell line 4T1 improved the tumor immune microenvironment, which may partly explain the cause of resistance to ICB therapy and provide a theoretical basis for combination therapy." (PMID 37875591, 2023). "Further tumor metastasis assays showed ZDHHC9 promotes peritoneal, pulmonary, and hepatic metastases in GC." (PMID 41535416, 2026). "The findings suggested that ZDHHC9 mRNA expression was elevated in most tumor tissues (P < 0.05), including BC, relative to corresponding normal tissues, both within the TCGA dataset independently and in the combined TCGA-GTEx dataset." (PMID 40740766, 2025). "High ZDHHC9 expression was also correlated with features of an immune-evasive tumor microenvironment (TME)." (PMID 40740766, 2025). "This study highlights ZDHHC9 as a potential prognostic marker, a regulator of tumor immunity, and a biomarker of therapeutic response in BC, offering a promising avenue for improving BC diagnosis and treatment." (PMID 40740766, 2025). "Beyond its immunological effects, ZDHHC9 also exerts a direct pro-tumor effect by activating oncogenic signaling pathways." (PMID 40740766, 2025). "Multivariate analysis confirms ZDHHC9 as an independent adverse prognostic factor, adjusting for age, sex, and tumor resection status." (PMID 40335986, 2025). "ZDHHC9 knockdown converts “cold” to “hot” tumor microenvironments, inhibiting progression and extending survival." (PMID 40977744, 2025). "For example, ZDHHC9-mediated PD-L1 palmitoylation has been indicated to stabilize PD-L1 protein levels in tumor cells, thereby promoting the efficacy of immune checkpoint inhibitors." (PMID 40681504, 2025). "Flow cytometry assay and tissue immunofluorescence analysis were used to detect infiltration of multiple immune cells in tumor tissue at different levels of ZDHHC9 expression." (PMID 37875591, 2023). "ZDHHC9 expression displayed a negative association with the tumor immune cycle, particularly in step 5, where immune cell infiltration into tumor tissues was notably suppressed." (PMID 40740766, 2025). "Moreover, lower mRNA levels of Zdhhc9 were correlated with increased immune cell infiltration in tumor biopsies." (PMID 40828036, 2025). "Importantly, targeting ZDHHC9 is expected to have a dual impact: curbing tumor-intrinsic proliferation signals and mitigating tumor-induced immune evasion." (PMID 40740766, 2025). "Moreover, apoptosis experiments were performed, and found that ZDHHC9 knockdown markedly promoted apoptosis of tumor cells." (PMID 40740766, 2025). "Strikingly, this effect was abrogated when ZDHHC9 was silenced or when tumor cells were treated with Imatinib, suggesting that ZDHHC9 activity in tumor cells is required for secreting factor(s) – likely including MIF – that skew macrophages to an alternative (M2) phenotype." (PMID 40740766, 2025). "Additionally, given that high ZDHHC9 expression correlates with unfavorable prognosis in BC patients, nude mice were subcutaneously injected with either ZDHHC9 knockdown or control tumor cells." (PMID 40740766, 2025). "Thus, ZDHHC9 plays a crucial role in the tumor immune microenvironment, particularly in immune checkpoint regulation." (PMID 40335986, 2025). "Inhibition of ZDHHC9, a palmitoyl transferase, could interrupt the palmitoylation of PD-L1, sensitized tumor cells to immune T cell attacking." (PMID 37251324, 2023).